PTH (parathyroid hormone)
Diseases named in the same sentence as PTH in open-access papers (continued):
Sharing a sentence is not in itself a finding about the gene and the disease.
Hypocalcemia (continued). "An editorial posed the question of whether the increase in PTH levels and hypocalcemia during bisphosphonate treatment in patients with metastatic breast cancer could be predisposing factors to ONJ." (PMID 26827062, 2016). "Several factors such as decreased secretion of PTH and/or resistance to PTH action in kidney and bone may contribute to the hypocalcemia." (PMID 27679579, 2016). "Eight unrelated patients with hypocalcemia and low or inappropriately normal PTH levels in the absence of CASR mutations were studied by Sanger sequencing." (PMID 27803672, 2016). "It is unlikely that inappropriate PTH secretion is central to the development of equine neonatal hypocalcemia as PTH concentrations were elevated in the foals of this study and we have previously documented that PTH increases in response to illness in septic foals." (PMID 26046642, 2015). "Potentially this could be explained by a stimulatory effect of the EGTA induced hypocalcemia on the PTH secretion in a situation where the increased PTH would result in release of P from the skeleton, but could not induce phosphaturia as the rats were NX." (PMID 25885328, 2015). "We have shown that most foals with hypocalcemia have increased PTH concentrations indicating that other mechanisms may be involved." (PMID 26046642, 2015). "This patient’s 27-year-old daughter also had hypoparathyroidism, which was incidentally identified when she visited our hospital for a common cold at the age of 14 years; blood examination showed hypocalcemia (5.7 mg/dL) and hyperphosphatemia (6.8 mg/dL) with a low level of intact PTH (9 pg/mL)." (PMID 26514990, 2015). "We hypothesized that hypovitaminosis D, hypocalcemia, hyperphosphatemia, and increased PTH concentrations will be frequent in critically ill foals." (PMID 26046642, 2015). "This increase in PTH could be explained by hypocalcemia and/or hyperphosphatemia directly stimulating PTH secretion by the parathyroid chief cells." (PMID 26046642, 2015). "Moreover, another review of 458 patients undergoing thyroidectomy also found that 7% of patients with normal intact PTH levels developed hypocalcemia." (PMID 25691901, 2015). "Finally, in our PTH example, the binary outcome was hypocalcaemia by 48 h and was known for every patient." (PMID 25800943, 2015). "Autosomal dominant hypocalcemia type 1 (ADH1) is caused by germline gain-of-function mutations of the calcium-sensing receptor (CaSR) and may lead to symptomatic hypocalcemia, inappropriately low serum PTH concentrations and hypercalciuria." (PMID 26052899, 2015). "It is possible that there may be a different set-point for the calcium PTH relationship in the obese, as demonstrated in a calcium-citrate clamp that showed an exaggerated PTH response to hypocalcemia as compared to normal subjects." (PMID 25161666, 2014). "When hypocalcaemia occurs, serum PTH concentration increases and enhances reabsorption of calcium." (PMID 25069806, 2014). "This, in fact, is one of the important factors in the pathogenesis of hypocalcaemia and might result from either increased calcium influx into bone or skeletal resistance to parathyroid hormone." (PMID 25076664, 2014). "The rise in serum PTH may be a result of parathyroid cell re-proliferation stimulated by hypocalcemia in these patients." (PMID 24886230, 2014). "Prior work by our group suggested that a single one hour post-thyroidectomy parathyroid hormone (1 hr PTH) level could accurately stratify patients into high and low risk groups for the development of hypocalcemia." (PMID 24476535, 2014). "The pathophysiology of SRH is complex and involves phosphorus retention leading to hyperphosphatemia, ionized hypocalcemia, decreased circulating 1,25-dihydroxyvitamin D (calcitriol) concentration and increased concentrations of parathyroid hormone (PTH) and fibroblast growth factor 23 [FGF23,]." (PMID 25333360, 2014). "Other studies compared PTH percent change as predictor for hypocalcemia." (PMID 24476535, 2014).
Hypocalcemia (continued). "It is well known that vitamin D and calcium are potent regulators of PTH, suggesting that hypocalcemia and hypovitaminosis D combined with a slight decrease in renal function, as observed in VDD animals, may be responsible for the increase in PTH." (PMID 25048368, 2014). "However, when both factors were entered into multivariate analysis, PTH-SC (β coefficient = 1.919, OR 6.803, 95 % CI 1.570–29.412, p = 0.010) was the only independent factor for hypocalcemia." (PMID 22968355, 2013). "People with CKD also experience several biochemical imbalances—such as increased phosphorus (as a result of retention), low vitamin D and calcium (hypocalcemia), and increased parathyroid hormone—which lead to further health problems (such as a thinning of the bones) and pain." (PMID 23637579, 2013). "In our second analysis, we aimed to find out whether low preoperative 25-OHD level affected the accuracy of single qPTH in predicting hypocalcemia by comparing the AUC of PTH-SC when 25-OHD <15 ng/mL with the AUC of PTH-SC when 25-OHD ≥15 ng/mL." (PMID 22968355, 2013). "Although SHPT is a result of increased parathyroid hormone (PTH) synthesis due to phosphorus accumulation and hypocalcemia, other factors such as impairment of vitamin D metabolism and reduced PTH renal clearance may also exacerbate it." (PMID 24693502, 2013). "This may impair PTH response or result in target organ resistance to PTH, leading in turn to hypocalcaemia." (PMID 24073266, 2013). "Thus, it is necessary to assess maternal PTH levels in addition to Ca and phosphorus levels during investigation of neonatal hypocalcemia." (PMID 24072092, 2013). "Cinacalcet treatment was given in the included trials generally at increasing doses (usually 30 to 180 mg/d) targeted to serum PTH concentrations, with discontinuation of therapy in the event of PTH concentrations falling below a specific target and/or hypocalcemia or adverse event." (PMID 23637579, 2013). "Hypocalcemia may also be due to the impaired PTH action, similar to serum changes in calcium and PTH seen in the 1,25(OH)2D null mouse." (PMID 23741318, 2013). "Therefore, in the ambulatory setting, PTH-SC ≤1/>1 pmol/L was probably the single most accurate and most reliable test in predicting clinically relevant hypocalcemia." (PMID 22399155, 2012). "Therefore, the aim of our study was to evaluate prospectively the accuracy and reliability of quick PTH-SC in predicting clinically relevant postoperative hypocalcemia." (PMID 22399155, 2012). "PTH-SC is an accurate and reliable means of predicting clinically relevant hypocalcemia." (PMID 22399155, 2012). "In addition, calcium acetate can correct hypocalcemia which is a critical factor in stimulating PTH secretion and induction of parathyroid gland hyperplasia." (PMID 21324193, 2011). "Intermediate or subnormal PTH level is a less accurate predictor of hypocalcaemia." (PMID 20798772, 2010). "The reduction in ionised calcium as a result of hemodilution and chelation by acetate-containing fluid used in priming the CPB may be responsible for the rapid rise in PTH, as part of the normal physiological response to hypocalcaemia." (PMID 21110839, 2010). "Therefore, PTH assay can now be considered as a perioperative adjunct to predict normocalcaemia or hypocalcaemia with reasonable accuracy." (PMID 20798772, 2010). "Hypocalcemia, hyperphosphatemia and calcitriol deficiency may be founding CRF, and are the main reasons for increased PTH secretion; this in turn results in morphological changes in parathyroid glands." (PMID 20658024, 2010). "Hypocalcemia stimulates the release of PTH, resulting in increased effect of PTH on bone." (PMID 20062590, 2009). "Also, low immunoreactive parathyroid hormone levels in the presence of hypocalcemia confirmed a diagnosis of hypoparathyroidism." (PMID 19946579, 2009).
Hypocalcemia (continued). "Patients with this syndrome should be informed of the symptoms that might occur with hypocalcemia, have their calcium-parathyroid hormone axis periodically checked and receive genetic counseled as there is a 50% risk of having an affected offspring." (PMID 18053182, 2007). "Activating mutations of the CASR gene give rise to hypercalciuria and hypocalcemia because of the direct effect in TALH cells (where the CaSR can inhibit calcium absorption) and to the inhibition of PTH secretion, which induces additional downregulation of calcium absorption in the distal tubule." (PMID 17464515, 2007). "With upregulation, as in hypercalciuric hypocalcemia, the serum PTH levels are inappropriately low." (PMID 16921418, 2006). "Additionally, hypomagnesemia induces PTH resistance, resulting in hypocalcemia." (PMID 41601884, 2026). "Patients with a low preoperative PTH level may have subclinical parathyroid dysfunction or autoimmune thyroid disease (for example Hashimoto’s thyroiditis), making them more vulnerable to postoperative hypocalcaemia." (PMID 41229353, 2025). "Additionally, researchers have found that a reduction of up to 80% in postoperative PTH values can achieve 100% sensitivity for predicting hypocalcemia, supporting the notion that later PTH measurement may enhance diagnostic accuracy." (PMID 40091995, 2025). "Laboratory findings revealed severe hypocalcemia (1.28 mmol/L [ref: 2.15–2.57 mmol/L]), normophosphatemia (1.36 mmol/L [ref: 0.94–1.55 mmol/L]), mild hypomagnesemia (0.62 mmol/L [ref: 0.74–0.99 mmol/L]), and a low intact PTH level (0.84 pmol/L [ref: 2.72–7.97 pmol/L])." (PMID 40655406, 2025). "However, the evidence suggests that both HIV infection and cART, particularly TDF, contribute to abnormalities in PTH secretion, independent of traditional risk factors such as vitamin D deficiency or hypocalcaemia." (PMID 41295288, 2025). "While the mechanism is not fully understood, the sudden reduction in parathormone (PTH) levels leading to hypocalcemia and decreased bone turnover, together with an increased calcium loading in a patient at risk for abnormal mineralization, may promote vascular and soft tissue calcification." (PMID 40149691, 2025). "Therefore, it can lead to a decrease in parathyroid hormone levels and progression of hypocalcemia." (PMID 40126147, 2025). "Furthermore, hypocalcemia could also be attributed to the coexistent hypomagnesemia (which is known to impair the release of PTH and induce skeletal resistance to its actions or/and hypokalemia which is associated with increased urinary excretion of calcium." (PMID 40183914, 2025). "Furthermore, the pre-treatment levels of albumin-adjusted serum calcium and creatinine are the strongest predictors in denosumab-related hypocalcemia, but sex, age, vitamin D, PTH, alkaline phosphatase, or prior osteoporosis treatment do not have predictive value." (PMID 40149708, 2025). "Hypocalcemia may trigger considerable fluctuations of PTH with values up to several thousand pg/mL." (PMID 41303180, 2025). "Therefore, in the context of her history and initial PTH being inappropriately normal despite concomitant hypocalcemia led to suspicion for non-PTH mediated causes." (PMID 40492015, 2025). "Hence, the coactivator-independent effects responsible for the severe bone phenotype of VdrΔAF2 mice are likely its negative effects on mineral (re)absorption, which result in persistent hypocalcemia and hypophosphatemia even on the rescue diet, along with chronically elevated PTH levels." (PMID 39164247, 2024). "However, the clinical decision is taken according to the following domains: biochemical PTH level, clinical features of hypoparathyroidism (ie, acute as hypocalcemia symptoms or chronic as extrapyramidal symptoms), and the chronicity of the condition after thyroidectomy." (PMID 38371915, 2024). "Furthermore, hypomagnesemia can impair PTH function, further complicating hypocalcemia management." (PMID 39479146, 2024).
Hypocalcemia (continued). "Moreover, vitamin D resistance leads to hypocalcemia, osteomalacia, and increased PTH release." (PMID 39364464, 2024). "Additionally, when the vascular pedicle sustains an injury, compromising all glands through resection or unintended surgical manipulation, there is a sudden and substantial decrease in PTH levels, resulting in a more pronounced and rapid onset of hypocalcemia, consequently manifesting symptoms." (PMID 40071247, 2024). "When calcium levels are low, there is an increase in PTH production that then activates 1-α-hydroxylase in the renal tubules to increase the amount of active vitamin D. However, this is not possible when hypovitaminosis D causes sustained hypocalcemia leading to a more sustained increase of PTH." (PMID 39301310, 2024). "PTH is not a significant risk factor for hypocalcemia when the PTH level is 15 pg/mL or higher on the day after surgery (20% of patients in this group had hypocalcemia in the present results), suggesting that improving the 1,25(OH)2D levels before surgery will reduce the incidence of hypocalcemia." (PMID 38803480, 2024). "However, some patients still have postoperative hypocalcemia or low PTH, which may be because of the sensitivity of the parathyroid glands to transient ischemia." (PMID 38431572, 2024). "Although surgery was immediately effective in reducing calcium and PTH levels, it precipitated HBS, a well-described phenomenon in patients who undergo parathyroidectomy, where total serum calcium concentration falls rapidly and hypocalcemia persists with associated hypophosphatemia." (PMID 39129820, 2024). "Finally, some differences in active VD requirements for postoperative hypocalcemia at similar levels of PTH reduction may be partly explained by the rate of 1,25(OH)2D metabolism." (PMID 38803480, 2024). "In addition, hypomagnesemia reduces the ability of the parathyroid gland to secrete PTH in humans, even in the presence of hypocalcemia, and it is possible that similar mechanisms might also be present in dairy cows." (PMID 38672379, 2024). "Hence, post-operative hypocalcaemia may be better managed by using PTH levels as the primary decision-making tool, with calcium levels and clinical findings serving as adjuncts in the decision-making process." (PMID 39649119, 2024). "In all cases, univariate and multivariate analyses of all factors, including intraoperative factors that might determine the Ca concentration on the morning following surgery and hypocalcemia, showed that the amount of PTH decrease was a significant parameter in multivariate analysis." (PMID 38803480, 2024). "It has already been shown that this systematic prevention in perioperative is effective in reducing the incidence and severity of hypocalcemia after TT, associated or not with a central lymph node dissection, without inhibiting the secretion of parathyroid hormone; and allows for safe early exit." (PMID 38238721, 2024). "Notably, hypocalcemia with normal PTH levels (10-65 pg/mL) was observed in seven cases." (PMID 39262524, 2024). "However, on initial presentation, this patient had an elevated PTH of 242 pg/mL and a normal vitamin D level of 56 ng/mL, which suggests that the parathyroidectomy was not a probable cause of her hypocalcemia." (PMID 39355148, 2024). "Whilst the exact mechanism of hypocalcaemia in trauma is yet to be elucidated, various sources suggest potential mechanisms other than citrate chelation, such as dilution, colloid binding, lactate binding, acidosis, ischaemic reperfusion, and impaired parathyroid hormone secretion or action." (PMID 38319350, 2024). "In this sense, the possibility of using Mg as a hypocalcemia predictor has some advantages over PTH, such as lower cost and a much narrower band for normal plasma level in that small variations in its concentration could be sufficient to predict the need for Ca replacement." (PMID 36651710, 2023).
Hypocalcemia (continued). "Rheumatoid arthritis may cause hypocalcemia but may not affect PTH secretion because of other controlling factors." (PMID 37849009, 2023). "Notably, our experience indicates that a significant decrease in PTH levels following thyroid surgery may result in aggravated hypocalcemia, suggesting a potential residual PTH effect in PHP patients." (PMID 38137593, 2023). "Since PTH inhibits phosphate reabsorption and induces 25-dihydroxy vitamin D 1-α-hydroxylase (Cyp27b1) mRNA expression through the cAMP-dependent cellular mechanism, patients may develop not only hyperphosphatemia but also hypocalcemia." (PMID 37920253, 2023). "However, our data on dialysed patients showed that they had elevated PTH, phosphate, CTX, P1NP with hypocalcemia and vitamin D deficiency, which may require treatment optimisation." (PMID 37102048, 2023). "In addition to the major effect of parathyroid gland endocrinopathy, hypothyroidism and hypomagnesemia may play a role in hypocalcemia by suppressing parathyroid hormone and, thereby, are further contributing factors to hypocalcemia." (PMID 37176024, 2023). "Therefore, reduced synthesis of PTH ultimately manifests as hypocalcemia." (PMID 38030913, 2023). "A decrease in PTH (parathormone) levels below 15 pg/mL with concomitant hypocalcemia defines the group of patients with biochemical hypoparathyroidism, while patients with a decrease in calcium levels below 8.8 mg/dL should be classified in the group of patients with hypocalcemia." (PMID 37626794, 2023). "Furthermore, hypocalcemia modulates PTH secretion through posttranslational modification." (PMID 36015101, 2022). "The difference could be explained by various definitions of chronic hypoparathyroidism; some can include pseudohypoparathyroidism or only ‘PTH level below the lower limit of the laboratory standard, accompanied by hypocalcemia’ while we were in line with international consensus statement." (PMID 34939939, 2022). "Previous studies have shown that there are a number of risk factors for hypocalcemia following PTX, including age, serum alkaline phosphatase (ALP) activity, number of parathyroidectomy procedures performed, and the circulating parathyroid hormone (PTH) concentration." (PMID 36531501, 2022). "In addition to its current indication as second‐line treatment in patients with refractory hypocalcaemia, our results support the use of PTH replacement therapy in patients in whom hyperphosphatemia and increased urinary calcium excretion are a clinical concern." (PMID 35485213, 2022). "However, any PTH measurement from as early as 10 min post-surgery might be used to implement early treatment which will reduce the incidence and the severity of hypocalcemia." (PMID 35566513, 2022). "However, for those patients with PTH levels between 15 and 19 pg/ml, there was a small but not negligible risk of developing symptomatic hypocalcaemia (5.4%)." (PMID 35247092, 2022). "Importantly, our study, like previous reports, shows that short-term SP supplementation does not cause hypocalcemia, and does not change the PTH level, which indicates that the proposed phosphate loading protocol does not disturb the phosphate-calcium balance." (PMID 35057416, 2022). "Furthermore, PTH-SC might be a more precise and reliable marker in predicting postoperative hypocalcemia than serial Ca level monitoring; it might also abolish the need for multiple withdrawal of blood samples during hospital stay overnight." (PMID 34429957, 2021). "However, 25 patients (18.4%) with normal post-operative PTH levels had an incidental parathyroidectomy, suggesting that this is not the only factor contributing to the development of post-operative parathyroid dysfunction and hypocalcemia." (PMID 34575224, 2021).